LINC01549 (long independently transcribed non-coding RNA 1549)
Synonyms: C21orf37
Gene: Long non-coding RNA gene on chromosome 21 (17,438,752 to 17,450,104, forward strand). Ensembl gene ENSG00000232560.
Diseases named in the same sentence as LINC01549 in open-access papers:
LINC01549 is named in the same sentence as 2 diseases in open-access papers, as found by Europe PMC text mining. Sharing a sentence is not in itself a finding about the gene and the disease.
LINC01549 shares sentences with these, for which no sentence is quoted: cancer (1 paper); ovarian carcinoma (1).